HOXB3 (homeobox B3)
Description:
Sequence-specific transcription factor which is part of a developmental regulatory system that provides cells with specific positional identities on the anterior-posterior axis.
Synonyms: HOX2G; HOX2; Hox-2.7
Tractability: No criterion of Open Targets' tractability assessment is met for any kind of drug.
Gene: Protein-coding gene on chromosome 17 (48,548,870 to 48,604,912, reverse strand). Ensembl gene ENSG00000120093.
Subcellular location: Nucleus
Subcellular location (Human Protein Atlas): Nucleoplasm
Pathways (Reactome):
Developmental Biology: Activation of anterior HOX genes in hindbrain development during early embryogenesis
Gene Ontology:
Molecular function: DNA-binding transcription activator activity, RNA polymerase II-specific; RNA polymerase II cis-regulatory region sequence-specific DNA binding; DNA-binding transcription factor activity, RNA polymerase II-specific; DNA binding; DNA-binding transcription factor activity
Biological process: angiogenesis; positive regulation of transcription by RNA polymerase II; anterior/posterior pattern specification; embryonic skeletal system morphogenesis; regulation of transcription by RNA polymerase II; regulation of DNA-templated transcription
Cellular component: nucleoplasm; chromatin; nucleus
Genetic constraint (gnomAD): Loss-of-function variants: 17 observed, 26.42 expected, observed/expected ratio (o/e) 0.64, 90% interval 0.44 to 0.96. The upper end of that interval is the gene's LOEUF score, 0.96, which puts it in group 4 of 6, group 1 being the genes least tolerant of losing a copy. Missense variants: 637 observed, 594.69 expected, observed/expected ratio (o/e) 1.07, 90% interval 1 to 1.14. Synonymous variants: 317 observed, 272.85 expected, observed/expected ratio (o/e) 1.16, 90% interval 1.06 to 1.27.
Homologues: Orthologues: chimpanzee HOXB3 (98% identical), pig HOXB3 (97% identical), mouse Hoxb3 (95% identical), rabbit HOXB3 (94% identical), rat Hoxb3 (94% identical), dog HOXB3 (94% identical), zebrafish hoxb3a (66% identical), tropical clawed frog hoxb3 (59% identical). Paralogues in human: HOXA3 (53% identical), HOXD3 (51% identical), HOXB2 (22% identical), PDX1 (21% identical), HOXA2 (21% identical), HOXD4 (18% identical), HOXA1 (18% identical), HOXA4 (16% identical), HOXB1 (16% identical), HOXB4 (16% identical), GSX2 (16% identical), HOXB5 (16% identical), and 30 more.
Diseases named in the same sentence as HOXB3 in open-access papers:
HOXB3 is named in the same sentence as 56 diseases in open-access papers, as found by Europe PMC text mining. Sharing a sentence is not in itself a finding about the gene and the disease. The quoted sentences say what the papers report.
leukemia (10 papers, 2010 to 2026). A malignant (clonal) hematologic disorder, involving hematopoietic stem cells and characterized by the presence of primitive or atypical myeloid or lymphoid cells in the bone marrow and the blood. "Bioinformatics analysis demonstrated the association of HOXB3 hypomethylation with several leukemia-related genes (HOXB family genes, miR-10, miR-196a, miR-1, miR-193b and miR-379) in AML." (PMID 41601621, 2026). "Moreover, several leukemia-related miRNAs, such as miR-10, miR-196a, miR-1, miR-193b and miR-379, have also been found to be associated with HOXB3 dysregulation." (PMID 41601621, 2026). "Overexpression of HOXB3 partially blocked miR-375-induced arrest of proliferation and reduction of colony number, suggesting that HOXB3 plays an important role in miR-375-induced anti-leukemia activity." (PMID 29439669, 2018). "Overexpression of HOXB3 partially prevents anti-leukemia effects by miR-375 and knockdown of HOXB3 resembles the anti-leukemia activities of miR-375, suggesting that HOXB3 is functionally important target of miR-375." (PMID 29439669, 2018). "Having shown that miR-375 negatively regulated HOXB3 expression and inhibited proliferation and colony formation, we then determined the role of HOXB3 knockdown in the anti-leukemia activity." (PMID 29439669, 2018). "In another study, HOXB3 was found to interact with DNMT3B to promote leukemia development." (PMID 40275933, 2025). "Although the exact function of HoxB3 in the CNS is not well understood, its growth regulatory action and high expression in lymphocytes and leukemia cells suggest that HoxB3 might be a marker of immune cell activation." (PMID 36326394, 2022). "To address whether HOXB3 also played a role in the early stages of leukemia initiation, we went back to normal CB cells nascently transduced with NLTB to test the effect of HOXB3 shRNAs on clonogenic cell growth." (PMID 31266935, 2019). "Taken together, these results support the notion that NLTB-induced HOXB3 gene expression is required for clonogenic expansion of T-progenitor cells undergoing the earliest stages of malignant transformation, and that this dependency persists in established leukemia cells." (PMID 31266935, 2019). "In leukemia cell lines, miR-375 expression is down-regulated, and miR-375 inhibits CDCA3 expression by downregulating HOXB3 expression, thereby suppressing cell proliferation." (PMID 34905505, 2021). "In this manner, the researchers successfully identified a regulatory circuitry involving miR-375, HOXB3, and CDCA3/DNMT3B plays a significant role in the development of leukemia and also presents a potential therapeutic approach for AML by targeting the restoration of miR-375 expression." (PMID 37705098, 2023).
acute myeloid leukemia (9 papers, 2018 to 2026). Acute myeloid leukemia (AML) is a group of neoplasms arising from precursor cells committed to the myeloid cell-line differentiation. "Conversely, mutations in the HOXB3 CRE were associated with reduced expression, consistent with HOXB3 acting as a tumor suppressor in MM, as in acute myeloid leukemia." (PMID 29654271, 2018). "However, HOXB3, a gene associated with acute myeloid leukaemia (AML), was among the 15,432 sites with FDR < 0.05." (PMID 39295308, 2024). "Humans possess 39 HOX genes across seven families, with specific genes like HOXB3, HOXB4, and HOXA1 to HOXA10 linked to adverse outcomes in diseases such as acute myeloid leukemia (AML)." (PMID 39200378, 2024). "HOXB3 also directly interacts with DNMT3B to promote the occurrence of leukemia in acute myeloid leukemia." (PMID 34722321, 2021). "In addition, HOXB3 overexpression promotes the proliferation and invasion of glioblastoma cells, acute myeloid leukemia, pancreas, prostate, ovarian, and lung cancer." (PMID 34722321, 2021). "Further, in acute myeloid leukaemia (AML), HoxB2 and HoxB3 were identified as negative regulators of the FLT3 receptor tyrosine kinase, with their mutations associated with carcinogenic events in around 30% of AML cases." (PMID 41535654, 2026). "Researchers have examined the role of HOX genes (HOXA9 and HOXB3) and MEIS1 in the pathogenesis of acute myeloid leukemia (AML) in murine models." (PMID 41226583, 2025).
breast carcinoma (9 papers, 2011 to 2025). "In summary, HOXB3 expression was decreased in breast cancer, and it was associated with poor prognosis." (PMID 33240685, 2020). "To further predict the underlying mechanisms of HOXB3 function in breast cancer, we conducted two enrichment analyses." (PMID 33240685, 2020). "Therefore, we verified the survival curve and found that low expression of the HOXB3 gene was associated with poor prognosis in breast cancer patients." (PMID 33240685, 2020). "The results showed that HOXB3 might be an independent risk prognostic factor for breast cancer (P = 0.03)." (PMID 33240685, 2020). "Metascape for GO analysis of GEO data provided possible mechanisms that HOXB3 could positively regulate cell adhesion, inhibit cell proliferation and activate immune response in breast cancer; moreover, GSEA included several cancer-associated pathways." (PMID 33240685, 2020). "Therefore, whether the loss of HOXB3 expression in breast cancer was mediated by the vitamin D signaling pathway and thus affected the occurrence and progression of breast cancer was worthy of further research." (PMID 33240685, 2020). "As for the target relationship between miR-375 and HOXB3, it has been elicited in the development of pancreatic cancer and breast cancer, which is in line with our finding." (PMID 35127344, 2022). "Previously, HOXB3 has been verified to be directly bound by miR-375 in both pancreatic cancer and breast cancer." (PMID 35127344, 2022). "For instance, restoration of HOXB3 has been revealed to induce the ability of breast cancer cell migration and invasion." (PMID 35127344, 2022). "- Breast Cancer Gene-Expression Miner (bc-GenExMiner) v4.3: we used the “analysis-correlation-targeted” module to get the total correlation heatmap of HOXB3 expression with clinicopathologic parameters." (PMID 33240685, 2020). "- GEPIA: the box plot in “Expression DIY” of “Expression Analysis”, enter the “HOXB3” in “gene” module and get the box plot of the differential expression of HOXB3 in normal breast tissue and breast cancer." (PMID 33240685, 2020). "HOXB3 expression was analyzed in breast cancer patients compared with healthy breast tissue in the GEPIA database." (PMID 33240685, 2020). "Both bioinformatics analyses and western blot showed that HOXB3 was lost in breast cancer compared to normal breast tissue." (PMID 33240685, 2020). "- Kaplan-Meier Plotter: the mRNA gene chip of “Start KM Plotter for breast cancer” module was used to analyze the prognostic value of HOXB3 mRNA expression in all breast cancers." (PMID 33240685, 2020). "The correlation between HOXB3 expression and immune cells related gene markers in breast cancer (TIMER database)." (PMID 33240685, 2020). "In summary, we found that HOXB3 expression was decreased in breast cancer through data analysis and molecular biology experiments." (PMID 33240685, 2020). "Therefore, we further investigated the expression of HOXB2 and HOXB3 and their correlation with the clinical characteristics of patients with breast cancer." (PMID 38322121, 2024). "Since the expression of HOXB3 was lost in breast cancer, it was unknown whether low expression of HOXB3 indicated a poor prognosis." (PMID 33240685, 2020). "A relatively lower mRNA level of HOXB3 was correlated with HER2 or basal-like breast cancer." (PMID 33240685, 2020). "Taken together, these are important pathways in oncology research, which meant that HOXB3 might play an important role in the progression of breast cancer." (PMID 33240685, 2020). "It was suggested that the HOXB3 gene might have lower expression in aggressive breast cancer subtypes." (PMID 33240685, 2020). "In addition, we used the “analysis-expression-targeted” module to find the relationship between HOXB3 and the clinicopathologic parameters of breast cancer." (PMID 33240685, 2020). "At present, there are few studies on the HOXB3 gene in breast cancer." (PMID 33240685, 2020).
breast carcinoma (continued). "All the cancer-related KEGG pathways surrounding HOXB3 indicated that it might play an important role in breast cancer." (PMID 33240685, 2020). "Moreover, western blot showed that HOXB3 was highly expressed in normal breast tissues, moderately expressed in luminal breast cancer, and lowly expressed in TNBC." (PMID 33240685, 2020). "This study aims to explore the role of the HOXB3 gene in breast cancer." (PMID 33240685, 2020). "Whether HOXB3 expression can be used as a prognostic biomarker for breast cancer patients needs further validation in prospective studies." (PMID 33240685, 2020). "Our study also analyzed HOXB3 in different subtypes of breast cancer." (PMID 33240685, 2020). "Consistent with previous results that miR-375 presents anti-cancer activity through targeting HOXB3 in pancreatic cancer and breast cancer, our data indicate that overexpression of miR-375 inhibits cell proliferation and colony formation through inhibiting HOXB3 expression." (PMID 29439669, 2018). "By qRT-PCR, we confirmed that HOXB3 had the highest expression in the immortalized breast epithelial cell line MCF-10A, whereas expression was lower in the luminal breast cancer cell lines T47D and MCF-7 and the lowest in the triple negative breast cancer (TNBC) cell lines MDA-MB-231 and SUM-159." (PMID 33240685, 2020). "In addition to miR-375, miR-7 and miR-218 target HOXB3 in breast cancer cells and miR-10b binds 3′-UTR of HOXB3 and decrease HOXB3 expression in endometrial cancer." (PMID 29439669, 2018).
glioblastoma (7 papers, 2019 to 2023). The most malignant astrocytic tumor (WHO grade IV). "HOXB3 has also been associated with the regulation of cell proliferation and increased HOXB3 activity promoted cell proliferation in some pathological conditions like glioblastoma." (PMID 37733420, 2022). "For instance, silencing of HOXB-AS1, HOXB2, or HOXB3 can lead to inhibition of cell proliferation and apoptosis stimulation of glioblastoma." (PMID 36045719, 2022). "As HOXB3 in glioblastoma, its knockout leads to cancer cell suppression." (PMID 34722321, 2021). "Notably, it was recently suggested that HOXB3, a HOX gene ranked at the top of the PB list (although it is ranked 72 in the PR list and 45 in the GB list), promotes tumor cell proliferation and invasion in glioblastoma." (PMID 30961526, 2019).
prostate carcinoma (7 papers, 2018 to 2024). A carcinoma that arises from epithelial cells of the prostate gland. "But some scholars believe that HOXB3 promotes prostate cancer cell progression by transactivating CDCA3." (PMID 38254070, 2024). "The mRNA and protein expressions of HOXB3 are significantly upregulated in primary prostate cancer tissues compared with the adjacent normal prostate tissues." (PMID 34187591, 2021). "The mRNA and protein expressions of HOXB3 are significantly increased in primary prostate cancer tissues compared with the adjacent normal prostate tissues." (PMID 29439669, 2018). "Furthermore, overexpression of HOXB3 promotes prostate cancer proliferation through transcriptional activation of cell division cycle associated 3 (CDCA3)." (PMID 29439669, 2018). "Another study also found that HoxB3 can bind to the CDCA3 promoter region and transactivate CDCA3 expression to induce prostate cancer progression." (PMID 32716971, 2020). "In prostate cancer (PCA), our previous study observed that HOXB3 could promote tumor recurrence in hormone-naïve PCA partly through transactivating CDCA3 expression." (PMID 36973255, 2023).
pancreatic cancer (6 papers, 2012 to 2025). "In PDAC, aberrant expression of several HOX transcription factors has been described and functional studies have shown that HOXA10, HOXB7, and HOXC11 promote pancreatic cancer development while HOXA1, HOXB1, and HOXB3 act as tumor-suppressors." (PMID 40619489, 2025).
ovarian carcinoma (5 papers, 2017 to 2021). A malignant neoplasm originating from the surface ovarian epithelium. "Specifically, upregulation of HOXA10 and HOXB3 genes and downregulation of HOXC5 were significantly associated with unfavorable survival outcomes in patients with ovarian cancer." (PMID 29050303, 2017). "In conclusion, dysregulated expression of the HOXA10, HOXB3, and HOXC5 genes was significantly associated with favorable or unfavorable overall survival in a large ovarian cancer cohort from TCGA." (PMID 29050303, 2017). "Multivariate analysis demonstrated that HOXB3 (HR = 1.09, 95% CI 1.01–1.17, p = 0.027) overexpression is closely associated with shorter PFS, and HOXB3 overexpression decreased the sensitivity of ovarian cancer to cisplatin and attenuates the generation of cisplatin-induced ROS." (PMID 34187591, 2021). "Many studies have found that HOXB cluster members are involved in the tumorigenesis or progression of ovarian cancer, including HOXB2, HOXB3, HOXB4, HOXB7, and HOXB8." (PMID 33815481, 2021). "Results show ERα occupancy in HOXB3, TGM1, TWIST2, and WT1 gene promoters, which are all relevant for ovarian cancer, and DOT1L co-binding with ERα only in the TWIST2 and WT1 promoter regions." (PMID 31689915, 2019).
colon cancer (4 papers, 2021). "Long noncoding RNA (lncRNA) UCA1 promoted colon cancer progression through sequestering miR-28-5p to elevate the HOXB3 level." (PMID 34013042, 2021). "Among the top 10 lncRNAs predicted by VGAELDA, UCA1 facilitates the progression of colon cancer through upregulating miRNA miR-28-5p and HOXB3." (PMID 33745450, 2021).
cleft lip (3 papers, 2021 to 2022). Congenital defect in the upper lip where the maxillary prominence fails to merge with the merged medial nasal prominences. "The statistically significant increase of transcription factor HOXB3 within unilateral cleft lip affected tissue signifies their association with this specific type of cleft." (PMID 37733420, 2022). "HOXB3 could be more associated with morphopathogenesis of unilateral cleft lip during postnatal course of the disorder." (PMID 37733420, 2022). "The Mann–Whitney U test indicated a statistically significant difference in the number of HOXB3 immunopositive surface epitheliocytes between the controls and the unilateral cleft lip tissue group (U=20.0, p=0.004)." (PMID 37733420, 2022). "In the bilateral cleft lip tissue group the median number of HOXB3 positive cells in the surface epithelium was moderate (++) and it ranged from a few (+) to moderate to numerous (++/+++) number of immunopositive epitheliocytes." (PMID 37733420, 2022). "The median number of HOXB3 positive connective tissue cells in the unilateral cleft lip tissue group was moderate (++) and it ranged from a few (+) positive cells to numerous to abundant (+++/++++) HOXB3 positive cells." (PMID 37733420, 2022). "In the unilateral cleft lip tissue group the median number of HOXB3 positive epitheliocytes was moderate to numerous (++/+++) and it ranged from a few (+) to numerous to abundant (+++/++++) HOXB3 positive surface epitheliocytes." (PMID 37733420, 2022). "This role of HOXB3 in controlling cell proliferation has also been established in the context of cleft lip and palate." (PMID 34834487, 2021). "A similar but stronger correlation was seen also in unilateral cleft lip tissue which could imply some similarities of HOXB3 regulatory role in the developing of both lip and palate." (PMID 37733420, 2022). "Median values of semiquantitative evaluation for BARX1, DLX4, FOXE1, HOXB3, and MSX2 immunoreactivity within the control tissue group, unilateral cleft lip tissue group, bilateral cleft lip tissue group, and cleft palate tissue group." (PMID 37733420, 2022). "The results from our study could indicate that HOXB3 might be involved with epithelial tissue and connective tissue interactions during the formation of the lip and disruption of HOXB3 function could be a part of unilateral cleft lip morphopathogenetic mechanisms." (PMID 37733420, 2022). "The aim of this study was to detect and compare the immunohistochemical expression of cleft candidate gene coded proteins (DLX4, MSX2, HOXB3, SHH, PAX7, SOX3, WNT3A, and FOXE1) in the non-syndromic unilateral cleft lip patient tissue and control group tissue." (PMID 33917041, 2021). "Amongst these genes, DLX4, HOXB3, and MSX2 have been recently shown to be involved in the etiology of non-syndromic cleft lip and palate." (PMID 34834487, 2021). "This could indicate a close interaction between three factors – FOXE1, HOXB3, and MSX2 within bilateral cleft lip tissue." (PMID 37733420, 2022).
glioma (2 papers, 2020 to 2023). A benign or malignant brain and spinal cord tumor that arises from glial cells (astrocytes, oligodendrocytes, ependymal cells). "Many HOMEOBOX (HOX)-related genes (HOXD11, HOXD9, HOXC10, HOXC11, HOXC6, HOXB3, HOXA2, HOXA1) were associated with a glioma grade and significantly overexpressed in GIV (Wilcoxon rank-sum and BH padj < 0.05)." (PMID 36850002, 2023).